CDK4 (cyclin dependent kinase 4)
Diseases named in the same sentence as CDK4 in open-access papers (continued):
Sharing a sentence is not in itself a finding about the gene and the disease.
cancer (continued). "Taken together, as a new CDK4/6 and PI3K/AKT multi-kinase inhibitor, aminoquinol is a potential drug for HCC treatment alone or in combination with 5-Fu, sorafenib and potentially other targeted anti-cancer drugs." (PMID 34335258, 2021). "Moreover, the downstream target genes of Akt, including CDK4, MMP‐2 and MMP‐9, are involved in cancer cell proliferation, migration and invasion." (PMID 34709758, 2021). "Notably, the current CDK4 inhibitors such as ribociclib, abemaciclib, and palbociclib have been approved by the US FDA for the clinical treatment of cancer, achieving exciting results." (PMID 34784846, 2021). "Furthermore, significantly elevated expressions of CDK2, CDK4, and CDK6 are well documented in HCC and many other cancers, and they are the causal factors for the development and progression of cancer." (PMID 33579185, 2021). "Lower binding of p21 to CDK4 in mesenchymal-like cancer cells is only sufficient to maintain the activity of the CDK4 complex but is not enough to exert an inhibitory effect on the downstream pathway." (PMID 34309585, 2021). "Galangin effectively suppressed the phosphorylation of Thr-179 in the Smad3 linker region by reducing the phosphorylation of CDK4, resulting in an enhanced TGF-β1 signal to promote apoptosis and the growth inhibition of cancer cells (prostate cancer and pancreatic cancer)." (PMID 33494431, 2021). "As FGFR1 can stimulate the proliferation capacity of cancer cells, inhibiting both FGFR/FGF and the CDK4/6 pathways might be an effective approach to preventing or circumventing resistance to a single agent." (PMID 34123801, 2021). "Several cancer types such as non-small cell lung cancer, colorectal carcinomas, melanomas, and breast cancer involve decreased levels of endogenous CDK inhibitors, as well as CDK4 overexpression." (PMID 32349307, 2020). "Together, these data suggest that there is a functional linkage between CDK4/6 activity and disparate gene expression programs suggesting possible new approaches for cancer treatment related to non-canonical features or CDK4/6-RB axis." (PMID 32242058, 2020). "As almost all human cancers carry abnormalities in the pRB/E2F pathway components including INK4A, CCND, CDK4/6, RB1, or E2Fs, genetic of functional inactivation of the pRB/E2F pathway seems to be indispensable for deregulated proliferation in most cancer settings." (PMID 33003565, 2020). "CDK4/6–phosphorylated RB1 has been shown to promote anticancer immunity by inhibiting nuclear factor-κB activation and programmed death-ligand 1 expression, further indicating the immunological relevance of palbociclib during cancer treatment." (PMID 33282875, 2020). "Of note, CDK4/6 inhibitors exhibited similar opposite connectivity, suggesting these agents may also be effective against PRR11-amplified cancers." (PMID 33127913, 2020). "Palbociclib is an inhibitor of CDK4 and CDK6 approved by the FDA for use in many cancer types." (PMID 32413516, 2020). "Cell cycle deregulation is a common feature of cancer and a number of cell cycle CDK inhibitors have been approved as cancer therapeutics, most prominently CDK4/6 inhibitors, exemplified by palbociclib, for the treatment of advanced oestrogen receptor positive (ER+) breast cancer." (PMID 31530935, 2020). "Cyclin D1, a member of the cyclin family (D1, D2, and D3) which functions as a regulatory subunit and forms a complex with CDK4 or CDK6 for regulating cell cycle transition from the G1 to S phase, is frequently overexpressed in cancer cells and dysregulates CDK activity." (PMID 31840737, 2020). "CDK4 and its close homologue CDK6 play a crucial role in various cancer types." (PMID 33255177, 2020). "The CDK4/6-RB axis is critical for cell cycle entry and not surprisingly most cancers subvert this axis to promote proliferation; for instance, 19% of BC show amplification of CDK4 and CCND1 amplification is associated with endocrine resistance." (PMID 32307447, 2020).
cancer (continued). "Different from targeting CCND1 transcription or CDK4/6, antagonizing DILA1 may be an alternative or complementary way to downregulate Cyclin D1 protein in cancer treatment." (PMID 33139730, 2020). "Therefore, we conclude that the suppressive effects of CDK4 and CDK6 expression by miR-623 not only affect cancer cell proliferation, but also influence cancer cell migration and invasion." (PMID 32501811, 2020). "Palbociclib, a CDK4/CDK6 inhibitor, demonstrated a potent effect in some cancer drugs." (PMID 33597968, 2020). "In addition, MYC has also been connected to the CDK4/6 and that way to CCND1 through these cancer studies." (PMID 30976209, 2019). "SRX3177 is a “first in class” triple PI3K-BRD4-CDK4/6 inhibitor, for combinatorial inhibition of three oncogenes promoting cancer cell growth: phosphatidylinositol-3 kinase (PI3K), cyclin-dependent kinases 4 and 6 (CDK4/6), and the epigenetic regulator BRD4 in a single molecule." (PMID 30853982, 2019). "Gene expression analysis revealed that its mechanism of action might be attributed, in part, to downregulation of cancer-related genes, such as AKT1, BCL2L1, CCND1, CDK4, PLK1, and RHOA." (PMID 31527550, 2019). "However, the combination of MYR-p110α with a CDK4 activating mutation (R24C) led to increased tumorigenesis, demonstrating the interaction between the CDK4/Rb/E2F cascade and the PI3K signalling pathway observed in many human cancers." (PMID 31018529, 2019). "In cancer cells, knockdown of PVT1 expression inhibits the expression of cyclin D1 and CDK4, which suggests that PVT1 positively regulates the expression of cyclin D1 and CDK4." (PMID 31309249, 2019). "CDK4 and CDK6 are frequently overexpressed and dysregulated in diverse types of cancers." (PMID 30555164, 2019). "Although CDK4 and CDK6 have been considered to exert redundant functions in cell cycle regulation, there is accumulating evidence that the two proteins have different functions, particularly in cancer." (PMID 30858922, 2019). "Our findings reveal a molecular basis for cancer therapy through targeting glutaminolysis and mitochondrial respiration in ESCC with dysregulated Fbxo4-cyclin D1 axis as well as cancers resistant to CDK4/6 inhibitors." (PMID 30899002, 2019). "Decreased expression of Ki-67 in DE-EDCP treated 4T1 cells could be the result of G0/G1 cell cycle arrest and increased expression of CDK4/CDK6 inhibitor, p16, as it was previously shown in normal and cancer cells." (PMID 29963272, 2018). "Cyclin D1 is a proto-oncogene that is upregulated in various cancers and plays an important role in transition of G1 to S phase progression by binding to cyclin-dependent kinases such as CKD2 and CDK4 that promotes cell cycle through inhibition of phosphorylation of retinoblastoma protein (Rb)." (PMID 29515762, 2018). "Another consideration is the possible predictive utility of absent p16 expression for CDK4 inhibitors as suggested in clinical trials for breast and other cancers." (PMID 30062862, 2018). "Indeed, silencing of CCAT1 led to downregulation of many genes involved in cancer cell proliferation, survival and metastasis, such as EGFR, CDK4, YES1, PAK4, and HMGA1." (PMID 30190462, 2018). "As such, a large-scale clinical trial in obese patients without cancer is critical to determine the safety and efficacy of CDK4/6 inhibitors solely as an antiobesity therapeutic." (PMID 30185666, 2018). "In both non-cancer and cancer granulosa cells, leptin acts as a cyclinD/cdk4, cyclin A/cdk2 and E2F inhibitor." (PMID 28861689, 2017). "In the present study, we determined the dependency of the CDK4-retinoblastoma (CDK4-RB) axis in the suppression of cancer growth by fascaplysin, and identified TRKA and VEGFR2 as novel target molecules, which are directly targeted by fascaplysin." (PMID 28961193, 2017).
cancer (continued). "Interestingly, our results revealed that fascaplysin rapidly decreased cell viability and increased apoptosis when compared to other CDK4 inhibitors, such as PD0332991 and LY2835219, in various cancer cells." (PMID 28961193, 2017). "A novel prediction of the model is that PI3K + CDK4/6 inhibition is a very effective combination treatment because of its ability to both induce cancer cell death and cell cycle arrest by suppressing two parallel proliferation regulator complexes (cyclin E and CDK2, and cyclin D and CDK4/6)." (PMID 29623959, 2017). "Although CDK4 and CDK6 can potentially bind the same D type cyclins to regulate G1‐S phase progression, it is well established that each CDK and each D cyclin plays unique roles, both in normal development and during cancer progression." (PMID 28778953, 2017). "Moreover, OCT4 promoted cyclin D1 (CCND1) expression and activated cyclin-dependent kinase 4/6 (CDK4/6) activity to accelerate cell cycle progression and promote the proliferation and division of cancer cells." (PMID 29069758, 2017). "Our data, showing that CDK6 phosphorylates and thereby stabilizes FOXO3, are highly reminiscent of the effects elicited on FOXM1, a related transcription factor, that, following phosphorylation by CDK4 and CDK6, is stabilized and transactivated to prevent senescence of cancer cells." (PMID 28778953, 2017). "Moreover, treatment of two different cancer cell lines, MCF7 (breast) and SK-HEP-1 (liver), with a CDK4/6 inhibitor (Palbociclib or Palbo), mimicking TIS, also triggered endogenous upregulation of β3." (PMID 28273461, 2017). "The effect of CDK4/6 inhibitor in more TNBC models and other cancers needs to be further tested." (PMID 28067227, 2017). "Data indicate that this may be mediated, at least in some of these cancers, by deregulation of multiple alternative mitogenic pathways (for example, HER2, PI3K/AKT, and so on) that can potentiate cyclin D1:CDK4/6 signaling in an ER-independent fashion." (PMID 26857361, 2016). "The absence of Cyclin Ds or CDK4/6 has only modest effects on early mouse development despite their universal function in primary and cancer cells." (PMID 26883361, 2016). "Since RB is the main target of CDK4/6, cancers that have lost RB, proliferate independently of CDK4 and -6 and consecutively do not respond to CDK4/6 inhibition." (PMID 27429659, 2016). "Because CDK4 plays an important role in G1/S phase transition by associating with CDK6, deregulation of the CDK4/6 signaling pathway is one of the most common changes found in human cancers, including NSCLC, CDK4/6 were also considered the most desirable targets for cancer therapies." (PMID 27049724, 2016). "Although there are substantially increased progression-free survival rates of cancer patient populations in several studies, biomarkers that predict a positive response to CDK4/6 inhibitor treatment are currently not known." (PMID 25562820, 2015). "As we all known, CDK4 plays a key role in mammalian development and cancer, but CDK4-null mutant mice are viable and cell proliferation is not significantly affected in vitro due to compensatory roles played by other CDKs(mainly CDK6)." (PMID 26036633, 2015). "Furthermore, fascaplysin showed promising specific cyclin-dependent kinase 4 (CDK4) inhibitory activity with IC50 of 0.35 μM and it correspondingly blocked the growth of various cancer cells at the G0/1 phase of cell cycle." (PMID 24608973, 2014). "However, miR-497 can also attenuate the malignancy of cancers by regulating other targets, such as TARBP2, DICER, BCL2, CCND1, CCNE1, CDC25A, CCND3, CDK4." (PMID 24667580, 2014). "It has been reported that overexpression of CDK4/6 and CCND1 and deregulated E2F could contribute to cancer progression." (PMID 24826192, 2014). "CDK4 and CDK6 control the G1-S transition through the cell cycle and recent studies of genetically-engineered mice suggest that CDK4 or CDK6 is used to drive the cell cycle in each type of cancer." (PMID 24765199, 2014).
cancer (continued). "While selective CDK4/6 inhibition might be effective against certain malignancies, broad-spectrum CDK inhibition will likely be required for most cancers." (PMID 24605326, 2014). "Ryuvidine was shown to cause cell death in a panel of cancer cell lines and this cytotoxic activity is also present in cell lines, such as HeLa cells that lack a functional Rb pathway, suggesting that the main mechanism of action of Ryuvidine may not be related to CDK4 inhibition." (PMID 24902048, 2014). "The results showed that knockdown of CDK6 but not CDK4 reduced RB phosphorylation and inhibited carcinoma cell growth." (PMID 24765199, 2014). "Cdk4 overexpression following transfection is accompanied by concomitant increase in Cdk1 expression in RAMA37 cells and disruption of Cdk1/Cdk4 co-expression can be observed in human cancer cells undergoing spontaneous cell death." (PMID 21668989, 2011). "Cancer cell killing by PRGPRP, in a cyclic amphiphilic cassette, requires cells to be in cycle but does not perturb cell cycle distribution and is accompanied by altered relative Cdk4/Cdk1 expression and selective decrease in ATP levels." (PMID 21668989, 2011). "Studies in other cancer cell lines measuring cell cycle effects of individual CDK2 depletion showed little change in cell cycle profiles of asynchronous cells due to compensation by other CDK family members, including CDK1 and CDK4/6." (PMID 20010939, 2010). "Together with its corresponding binding partner cyclin-dependent kinases, CDK4 and CKD6, Cyclin D1 acts as a crucial cell cycle regulator which has been regarded to take an important part in the development and progression of several cancers." (PMID 20105337, 2010). "The analysis performed to exclude association of the CDK4 IVS4-nt40 AA genotype with the subset of non-obese cancer and tumors/cancer was not significant (data not shown)." (PMID 19327170, 2009). "After screening a panel of human cancer cell lines for CDK4 and CDK6 expression (data not shown), the U20S cell line was selected, as it accumulated approximately threefold higher levels of CDK6 compared to the WMM1175 cell line." (PMID 18843795, 2008). "Specifically, we focused on four previously-studied, targeted anti-cancer drugs for which our model includes primary targets and significant off-targets: trametinib (MEK inhibitor), alpelisib (PI-3Kα inhibitor), neratinib (EGFR/ErbB2/ErbB4 inhibitor), and palbociclib (CDK4/6 inhibitor)." (PMID 40880521, 2025). "Indeed, the success of CDK4/6 inhibitors in ER-positive/HER2-negative breast cancers has been critically based on the concomitant inhibition of ER, as a crucial inputting pathway in these cancers." (PMID 40699853, 2025). "In this cohort study of 5015 patients who were treated with CDK4/6 inhibitors, PARP inhibitors, or select TKIs between 2008 and 2024, incidence and rates of progressive kidney dysfunction were higher among treated patients relative to a matched cancer-free cohort." (PMID 41196597, 2025). "We found that this strategy results in modest improvement in outcomes, and certain subgroups (older patients, no chemotherapy, absence of any cancer involvement of the organs, certain mutations like ESR1 mutations, and non-use of palbociclib as the CDK4/6i) did better." (PMID 40427107, 2025). "Yet, it is not thoroughly understood whether other non-kinase functions of CDK4/6, such as the regulation of mitochondria activity or anti-cancer immunity, are location-related." (PMID 40894871, 2025). "However, it is not yet clear whether the expression of TMEM45A is related to the response to CDK4/6i treatment in HR + BRCA and whether TMEM45A regulates cancer metabolism." (PMID 39910045, 2025). "However, in-depth preclinical studies and early clinical research on the combined efficacy of CGs and CDK4/6 inhibitors for cancer treatment are still lacking." (PMID 40563591, 2025).
cancer (continued). "CDK4/6 inhibitors (CDK4/6i) have been effectively utilized in the treatment of hormone receptor-positive (HR+)/human epidermal growth factor receptor 2-negative (HER2-) metastatic or advanced BC patients, demonstrating the ability to delay cancer progression and enhance patient quality of life." (PMID 40223929, 2025). "Therefore, CDK4 and CDK6 are thought to be attractive targets for certain cancer therapies." (PMID 39593745, 2024). "Agents shown to increase cancer cell antigen presentation include hydroxychloroquine (by autophagy inhibition), poly(I:C) (by NF-κB activation downstream of dsRNA sensing), SMAC mimetics (by NF-κB activation), CDK4/6 inhibitors (by activation of endogenous genomic retroviral elements), and others." (PMID 38973593, 2024). "However, CDK4/6is are not cell-specific, so these agents can interfere not only with the cell cycle of cancer cells but also with the cell cycle of healthy cells in brain tissue." (PMID 39749028, 2024). "The hypothesis provides an explanation for how the cyclic amphiphilic peptide HILR‐056, derived from peptides with homology to a hexapeptide in the C‐terminal region of Cdk4, kill cancer cells but not normal cell by necrosis rather than apoptosis." (PMID 37279947, 2023). "Moreover, CDK4/6i treatment in MP41 cells led to noticeable Rb-protein reduction before the emergence of persisters, suggesting the contribution of Rb-protein reduction to CDK4/6i adaptation in cancer cells." (PMID 38030655, 2023). "Aggressive cancer cells expressing high c-Myc levels may readily initiate cell proliferation without CDK4/6 activity and show primary resistance to CDK4/6i." (PMID 38030655, 2023). "Importantly, CDK4 also promotes the self-renewal and proliferation of chemotherapy-resistant TNBC BCSCs, which are largely responsible for the recurrence and metastasis in this aggressive cancer." (PMID 36051751, 2022). "Although Cdk4-null mutant mice are viable and cell proliferation is not significantly affected in vitro due to compensatory roles played by other CDKs, this gene plays a key role in mammalian development and cancer." (PMID 36051751, 2022). "However, recent findings suggest the importance of a non-mitotic mechanism of paclitaxel in cancer cell death and pre-clinical data support rationale for a strategic paclitaxel and CDK4/6i combination." (PMID 36185294, 2022). "In cancer cells, CDC37 could prolong cell survival by activating the CDK4 signaling pathway." (PMID 35370699, 2022). "Indeed, we and others have found interdependent roles for CDK4/6 and AKT in a variety of cancers." (PMID 35158840, 2022). "Multiple preclinical studies support the hypothesis that CDK4/6i can improve the efficacy of standard chemotherapy treatments (such as paclitaxel and cisplatin) in TNBC and other cancer types by inducing apoptosis or potentiating DNA damage and causing increased cell death." (PMID 34932500, 2022). "As approved by the FDA for the treatment of advanced breast cancer, CDK4/6 inhibitors (Palbociclib, Abemaciclib and Ribociclib) functionate their anti-cancer effects by controlling tumor growth, which is not exclusively the result of their senescence induction." (PMID 36611926, 2022). "Similarly, targeting CDK4/6 using FDA-approved inhibitors in combination with HSP90 inhibition shows a class effect on HIF1α inhibition and cancer cell viability suppression not only in colorectal but also in various other cancer types, including Rb-deficient cancer cells." (PMID 34686682, 2021). "CDKN2A SCND leads to inactivation of both P16INK4a and P14ARF (two endogenous inhibitors for CDK4 and MDM2) in >90% CDKN2A-deleted cancers, it needs to study whether CDK4 and MDM2 inhibitor drugs could be used to prevent hematogenous metastasis of cancers." (PMID 35004325, 2021).